GATA3 (GATA binding protein 3)
Diseases named in the same sentence as GATA3 in open-access papers (continued):
Sharing a sentence is not in itself a finding about the gene and the disease.
tumor (continued). "Yet, the observation of GATA3 downregulation during tumour progression and predominant frameshift mutations have led to the view that GATA3 acts primarily as a tumour suppressor." (PMID 27588951, 2016). "There, GATA3-ext is associated with reduced disease-free survival compared to other GATA3 mutations, suggesting that these tumours display a different pathology with respect to recurrence." (PMID 27588951, 2016). "Recent data have shown that tumours that enrichcells with GATA3 mutations tend to be ductal cancers, whereastumours that possess FOXA1 mutations tend to be of the lobularsubtype." (PMID 26884552, 2016). "GATA3 mutations (8.9% across all tumours) were more frequent in IntClust1 (20.0%) and IntClust8 (19.5%), although patients in IntClust1 have worse outcomes." (PMID 27161491, 2016). "As an example, the GATA3-linked tumor-specific enhancer probe cg04747693 is within the H3K27Ac and GATA3 ChIP-seq signals in MCF7." (PMID 27833659, 2016). "In multivariate analysis, GATA3-positive expression was also detected as an independent risk factor influencing recurrence, in addition to tumor size." (PMID 27249072, 2016). "Our analysis shows that mutations in GATA3 are negatively associated with tumor size (measured by three tumor size phenotypes), tumor shape irregularity (measured by irregularity), and sum entropy that measures the randomness of enhancement texture." (PMID 26639025, 2015). "In the case of tumor associated repressed genes the analysis revealed Gata3 as master regulator and 63% or 15 out of 24 are part of the regulatory gene network." (PMID 26427040, 2015). "Based on altered regulatory activity of GATA3 upon tumorigenesis, we can postulate that in normal cells GATA3 is associated with tumor suppression activities (for example, differentiation, proper apoptotic processes, reduced proliferation)." (PMID 25410484, 2014). "While variants of GATA3 are known to influence tumor biology in ER-positive breast cancer, their role in TNBC heterogeneity remains to be studied." (PMID 24260093, 2013). "Among these genes, several tumor-related genes such as Gata3, Arnt and Tdgf1, epigenetic associated genes such as PHC1 and Uty were identified." (PMID 22952821, 2012). "Although loss of GATA-3 in early tumor leads to an inhibition of tumor formation, loss of GATA-3 in later stages leads to the acquisition of metastatic potential." (PMID 19243219, 2009). "Circulating tumor DNA (ctDNA) was assessed for GATA3 mutations via targeted sequencing." (PMID 40439821, 2025). "In addition to associations between GATA3‐low tumors and features of immune responses and metabolic alterations, we also confirmed known findings on tumor cell proliferation, stemness, EMT, and hypoxia in this BC subgroup." (PMID 41024411, 2025). "However, both wild-type and mutant products of GATA3 can be expressed and, depending on the nature of the mutation, the effects of GATA3 can shift from tumour suppressing to tumour promoting activities during tumorigenesis." (PMID 40585280, 2025). "Low GATA3 mRNA expression associated with downregulation of ER‐related genes, upregulation of transcriptional signatures reflecting hypoxia, and enrichment of gene sets reflecting tumor cell proliferation, epithelial‐mesenchymal transition, and stemness." (PMID 41024411, 2025). "Parameters for luminal tumor phenotype—which was linked to favorable disease outcome in studies analyzing RNA—such as uroplakin 1a, uroplakin 1b, or GATA3 were also unrelated to patient outcome in our cohort of more than 600 muscle-invasive carcinomas in recent studies." (PMID 39680294, 2025). "The rs1244159 genotype correlated with GATA3 protein levels, suggesting that this variant may regulate gene expression and influence tumor behavior." (PMID 40650155, 2025).
tumor (continued). "The adverse outcome in the basal subtype is usually attributed to GATA3 loss, promoting tumour suppressor gene downregulation and transition from epithelial to mesenchymal type leading to increased invasiveness and spread of the tumour." (PMID 39856762, 2025). "Two earlier studies utilized Gata3 deficient T cell models to demonstrate that Gata3 upregulation after T cell activation is key for the acquisition and maintenance of T cell effector function and differentiation in response to tumor or LCMV infection." (PMID 40012375, 2025). "GATA3 expression is known to be associated with epithelial ER expression and luminal phenotypes in BC but is to a lesser extent examined in relation to other tumor programs, for example, processes in the TME." (PMID 41024411, 2025). "GATA3-/FOXA1- is linked to tumor extensive necrosis and poor prognosis in UTUC and may serve as a potential biomarker for UTUC patients." (PMID 38425344, 2024). "Reconstitution of Gata3 enhances resistance of Brca1-deficient tumor cells to PARP inhibitor." (PMID 38627785, 2024). "Moreover, as shown, the release of GATA3 from exosomes derived from tumor-associated macrophages has been shown to promote tumor growth in the tumor microenvironment of high-grade serous ovarian carcinoma." (PMID 39335619, 2024). "Additionally, clinical‐pathologic characteristics, such as tumor grade, tumor stage, lymph node were taken into consideration and the diagnostic power of these miRNAs and GATA3 was evaluated using the ROC curve analysis." (PMID 38173189, 2024). "GATA3 has previously been associated with hormone receptor expression and lower tumor grade." (PMID 39149486, 2024). "As GATA3 also plays a role in the immune response and inflammatory reaction by a myriad of cells is a hallmark of UC, it is crucial to interpret the expression from the UC tumor cells." (PMID 37829946, 2023). "Despite GATA3’s known role as a tumour suppressor and diagnostic biomarker, the HPβCD-mediated suppression of GATA3 could prove beneficial." (PMID 37345165, 2023). "High macrophage infiltration in advanced tumor grade was associated with low GATA-3 expression." (PMID 36996051, 2023). "Moreover, high MI was related to a significant decrease in GATA-3 expression and related to advanced tumor grade indicating that increased MI is associated with poorly differentiated states in BC." (PMID 36996051, 2023). "We then tested whether reconstitution of Gata3 could restore AP-1 expression and epithelial features of Gata3 deficient tumor cells." (PMID 37353480, 2023). "Moreover, the knockout of Fra1 or reconstitution of Gata3 in Gata3 deficient tumor cells produced a very similar phenocopy in terms of reducing mesenchymal traits and inducing epithelial features in tumor suppression." (PMID 37353480, 2023). "Interestingly, GATA3 mutations were identified in larger lesions (Mann–Whitney, p = 0.038), consistent with a similar observation in invasive cancer and the larger tumor size of GATA3 mutated xenograft models." (PMID 35027560, 2022). "In addition to the immune cell types explored in this study, other cell types have been shown to affect NMIBC development, such as GATA3 + T cells, regulatory T cells, and tumor-associated macrophages." (PMID 35063012, 2022). "However, our knowledge of GATA3 mutations in tumorigenesis, tumor progression, and acquisition of drug resistance is limited." (PMID 35154280, 2022). "However, the associations between GATA3 and the tumor immune phenotypes in BLCA remain to be further elucidated." (PMID 35647011, 2022). "The GATA3 mutations may influence the expression profile of the tumor cells via impact on expression and activity rate of the GATA3 gene." (PMID 33462316, 2021).
tumor (continued). "Furthermore, both individual studies and our meta-analysis, propose that ERα and ERβ are markers of bad prognosis, while GATA3 is associated to lower risk of recurrence and more differentiated tumours." (PMID 34690921, 2021). "However, despite being associated with low metastatic potential and therefore a more favourable prognosis, GATA3-positive tumours are also associated with resistance to chemotherapy." (PMID 34099719, 2021). "Loss of GATA3 expression is also associated with BLBCs and tumor metastasis 13, 15-19." (PMID 34373738, 2021). "Regarding the female dogs, we sequenced 79 BC-related genes, and those with high number of variants shared by tumor fragments and plasma were GATA3 and mTOR (missense), SFRP1 (frameshift insertion), BRCA2 (multi hit), FOXC2, ATM, TGFBR3, and BRIP1 (missense and multi hit mutations)." (PMID 34680380, 2021). "However, tumours showed sex-associated differences in both GATA3, a transcription factor for Th2, and Tbet, a transcription factor for Th1 and CD8 activation." (PMID 32451467, 2020). "Most GATA3 mutations are rare or unique frameshift indels (insertion/deletions) distributed along the 3′ gene end, consistent with the classical mutational pattern of a tumor suppressor and therefore suggesting a LOF." (PMID 32587399, 2020). "Somatic GATA3 mutations occurred in HER2‐positive tumour components." (PMID 32058674, 2020). "Whether GATA3 mutations are true oncogenic drivers is also an open question: while some in vitro and in vivo data suggest a tumor-promoting function, in general they are associated with longer survival and better response to endocrine therapy." (PMID 32587399, 2020). "Previous studies have shown that FOXA1 expression was inversely associated with tumor size, histological grade, lymph node status, HER2 expression and lymph vascular invasion, while GATA3 expression showed an inversed association with tumor histological grade and HER2 status." (PMID 30819139, 2019). "Therefore NOD/SCID mice bearing DLD1 and SKBR7 xenografts were treated with either IgG or D/B mix to target VEGF-A signalling for 24 h before tumour collect and tumour-associated endothelial cell sorting for ChIP of NFκB and Gata3." (PMID 29367702, 2018). "IHC analysis showed a Th2 predisposition of tumor-infiltrating immune cells in therapy-naive patients: The mean (±SD, range) number of GATA3+ or T-bet+ immune cells and the GATA3/T-bet ratio was 340.2 (±288, 55–1258), 90.8 (±71.4, 12–289) and 5.5 (±5.3, 1.1–23.8) in all patients, respectively." (PMID 28005163, 2017). "Meanwhile, high GATA3 expression may be associated with positive ER, positive PR, smaller tumor size, and lower nuclear grade, all of which lead to improved survival." (PMID 28394898, 2017). "Whether both classes of GATA3 mutationshave the same effect on ER transcriptional activity and tumour outcome is currentlyunclear, but recent gene editing tools, such as CRISPR technologies, will permitinvestigation of these questions." (PMID 26884552, 2016). "In addition, GATA3 deficient mice have an impaired ability to kill tumour cells by CD8+ T-cells, indicating that GATA3 expression is required to mediate fully efficient cytolytic effector responses." (PMID 25803478, 2015). "Loss of GATA3 coincides with loss of differentiation and tumor metastasis." (PMID 24962896, 2014). "Importantly, it was demonstrated that the loss of GATA3 expression marks the loss of tumor differentiation and the onset of tumor dissemination." (PMID 25479686, 2014).
tumor (continued). "This set of mutations may impair GATA3 regulatory activity and lead to distinct tumor characteristics of the population which has mutated GATA3 allele." (PMID 25410484, 2014). "On the basis of mutation pattern, Vogelstein and colleagues classify GATA3 as a tumor suppressor." (PMID 24758297, 2014). "Among these genes, Gata3 and Arnt were well-known tumor-associated genes." (PMID 22952821, 2012). "One hypothesis would be that the higher the level of circulatory estrogen, the higher the risk of locoregional recurrence, whereas low tumor expression of aromatase and high tumor expression of GATA3 would reflect only the high plasma estrogen levels." (PMID 19638208, 2009). "A cluster enriched for genes associated with the luminal/ER+ tumor subtypes (N-acetyltransferase 1, estrogen receptor 1, putative G-protein-coupled receptor, trefoil factor 3, GATA binding protein 3, and X-box binding protein 1) was also present in this gene set." (PMID 17150101, 2006). "Moreover, germline polymorphisms within the GATA3 locus may contribute to inter-individual variation in gene expression, potentially influencing tumor biology and clinical outcomes." (PMID 40650155, 2025). "Additionally, GATA3 has been linked to tumor microenvironment (TME) dynamics, particularly its association with increased cancer-associated fibroblast (CAF) infiltration, which plays a crucial role in epithelial-mesenchymal transition and metabolically supports cancer cell proliferation." (PMID 40036264, 2025). "Furthermore, a tumor dependency signature constructed from these genes effectively stratified patient outcomes, with the high-dependency subgroup demonstrating enrichment in GATA3 mutations." (PMID 40657358, 2025). "Accordingly, GATA3 could function as tumor suppressor or oncogene depending on the mutation." (PMID 39931207, 2024). "Additional analysis demonstrated a significant association between tumor size (p < 0,001), lymph node (LN) metastasis (p = 0.004), clinical stage (p = 0.016), histological grade (p = 0.006), and survival (p < 0.0001), as well as distinct intervals of GATA-3 expression." (PMID 37483298, 2023). "The combined assessment of PR, ER, AR, GATA3, and PD-L1—as a manually predefined five-marker prognosis score—showed strong prognostic relevance (p < 0.0001) and was an independent risk factor (p = 0.0034) in a multivariate analysis including pT, pN, and tumor grade." (PMID 38137396, 2023). "Thus TSLP-promoted GATA3+ Tregs may also exert their immunosuppressive function through their crosstalk with tumor-associated DCs or myeloid-derived suppressor cells (MDSCs)." (PMID 36107619, 2022). "A challenge in investigating the function of GATA3 in vivo is that depletion of Gata3 in mice results in early lethality, proliferative defects, or apoptosis 18-21, 32, preventing the determination of its loss-of-function role in controlling cell fate in tumor development and progression." (PMID 34976209, 2022). "GATA3 overexpression is associated with positive ER (RR = 3.155; 95% CI = 1.680–5.923; P = 0.000), positive PR (RR = 3.949; 95% CI = 1.567–9.954, P = 0.004), lower nuclear grade (RR = 0.435; 95% CI = 0.369–0.514; P = 0.000), and smaller tumor size (RR = 0.816; 95% CI = 0.709–0.940; P = 0.005)." (PMID 28394898, 2017). "Therefore, it is tempting to speculate that in the prostate, GATA3 also has a tumor suppressor activity and loss of GATA3 is required for prostate tumorigenesis." (PMID 27374105, 2016). "Tumor-secreted LAMA4 engaged macrophage surface receptor ITGA6 to trigger GATA3 activation and reprogram macrophages toward a pro-metastatic and immunosuppressive phenotype." (PMID 41610310, 2026). "Immunohistochemical staining showed that the tumor cells were positive for BerEp4, GATA‐3, AE1/AE3, CAM5.2, ER (70%), AR (10%), PR (10%), and ki67 (10%)." (PMID 41239938, 2026).
tumor (continued). "A similar trend was observed for GATA3 (p < 0.05) and UPK3A, two well established BLCA-associated markers, supporting the presence of tumor-related transcriptional signatures in circulation." (PMID 41585944, 2026). "Histologic evaluation revealed poorly cohesive tumor cells infiltrating the lamina propria, and immunohistochemistry was positive for cytokeratin 7, GATA3, and estrogen receptor, confirming metastatic breast carcinoma." (PMID 41871938, 2026). "The tumor cells expressed hPL in 5/5 (100%) tumors, hCG in 5/5 (100%; focal in all tumors), and GATA3 in 5/5 (100%)." (PMID 41491402, 2026). "Genomic stability markers, such as BRCA1 and BRCA2, alongside luminal regulators like GATA3, decline progressively with both advancing age and tumor aggressiveness, reaching their lowest levels in TNBC." (PMID 41889413, 2026). "To our knowledge, we present the first description of GATA3 in relation to tumor immuno‐metabolic alterations in BC." (PMID 41024411, 2025). "The strong association between GATA3 and GATA4 expression supports their potential synergistic role in tumor biology." (PMID 41303462, 2025). "Tissue-based data from the Clinical Proteomic Tumor Analysis Consortium (CPTAC) database was evaluated for expression and phosphorylation of GATA3 and associated proteins." (PMID 40439821, 2025). "GATA3 is abundantly released via exosomes, where it drives the polarization of macrophages to the pro-tumorigenic M2 phenotype, enhancing tumor growth and immune evasion." (PMID 40330466, 2025). "On immunostaining, tumor cells were positive for GATA3, CD10, calretinin, TTF-1, and Pax-8 at various degrees, but were negative for ER." (PMID 39896229, 2025). "BMCA tumor cells are positive for breast tissue lineage markers, including GATA3, GCDFP-15, and mammaglobin." (PMID 41287704, 2025). "In young 67NR tumor-bearing mice, calcitriol increased Rora and Gata3 expression, while tacalcitol decreased Spp1." (PMID 40894304, 2025). "The tumour showed diffuse staining for the following immunohistochemical (IHC) markers: GATA‐3, CD56, synaptophysin, chromogranin, alpha‐methylacyl CoA racemase (P504S), and vimentin." (PMID 40588841, 2025). "IHC revealed positivity for pan-cytokeratin (PanCK) in the tumor, with rare tumor cells showing positivity for GATA3 and p63." (PMID 40893790, 2025). "Specifically, we focused on the role of key lncRNAs, miRNAs, and mRNAs in LUADBM progression, with a particular emphasis on the XLOC_006941/hsa-miR-543/NPRL3 axis, and the involvement of GATA3 and Th2 cells in shaping the tumor microenvironment." (PMID 39941924, 2025). "Immunohistochemical stains showed that the tumor cells were positive for GATA3, CAM5.2, epithelial membrane antigen (EMA), estrogen receptor (ER), and progesterone receptor (PR), consistent with metastatic breast carcinoma." (PMID 41515566, 2025). "Due to limited residual tissue, GATA3 immunostaining was successfully performed on 106 out of 111 tumor samples." (PMID 40856420, 2025). "In our specific case, staining with PSA, CK7, CK20, and GATA3 antibodies successfully differentiated the two tumor components in the lymph node." (PMID 41426316, 2025). "As our case report illustrates, considering the full morphologic and clinical context is essential to evaluating GATA3+ neoplasms in tissue biopsies at potential metastatic sites." (PMID 40691018, 2025). "Although GATA3 inhibits tumor formation in the breast, it appears to be involved in the tumorigenesis of lymphoid precursor cells." (PMID 41514651, 2025). "Blocking single or multiple type 2 cytokines in vitro did not impair the anti-tumour effect, but GATA3 KO completely abolished the anti-tumour activity mediated by ho4R." (PMID 40804519, 2025). "GATA3 can induce the expression of numerous tumor-suppressive genes by binding to and activating their promoters." (PMID 39800682, 2025).